PXDN (peroxidasin)
Description:
Catalyzes the two-electron oxidation of bromide by hydrogen peroxide and generates hypobromite as a reactive intermediate which mediates the formation of sulfilimine cross-links between methionine and hydroxylysine residues within an uncross-linked collagen IV/COL4A1 NC1 hexamer. In turns, directly contributes to the collagen IV network-dependent fibronectin/FN and laminin assembly, which is required for full extracellular matrix (ECM)-mediated signaling. Thus, sulfilimine cross-links are essential for growth factor-induced cell proliferation and survival in endothelial cells, an event essential to basement membrane integrity. In addition, through the bromide oxidation, may promote tubulogenesis and induce angiogenesis through ERK1/2, Akt, and FAK pathways. Moreover brominates alpha2 collagen IV chain/COL4A2 at 'Tyr-1485' and leads to bromine enrichment of the basement membranes. In vitro, can also catalyze the two-electron oxidation of thiocyanate and iodide and these two substrates could effectively compete with bromide and thus inhibit the formation of sulfilimine bonds. Binds laminins. May play a role in the organization of eyeball structure and lens development during eye development (By similarity).
Synonyms: hsPxd01; KIAA0230; MG50; PRG2; VPO; D2S448; D2S448E; PXN; ASGD7; COPOA
Tractability: Small molecule: it belongs to a druggable protein family. Antibody: UniProt places it where antibodies can reach, with high confidence; its Gene Ontology location is reachable by antibodies, with high confidence; UniProt predicts a signal peptide or a membrane-spanning region. PROTAC: ubiquitination databases record sites on it.
Gene: Protein-coding gene on chromosome 2 (1,631,887 to 1,744,852, reverse strand). Ensembl gene ENSG00000130508.
Subcellular location: Secreted, extracellular space, extracellular matrix; Endoplasmic reticulum; Cell surface; Secreted, extracellular space, extracellular matrix, basement membrane; Secreted, extracellular space, extracellular matrix (PXDN active fragment)
Pathways (Reactome):
Developmental Biology: Regulation of MITF-M-dependent genes involved in extracellular matrix, focal adhesion and epithelial-to-mesenchymal transition
Extracellular matrix organization: Crosslinking of collagen fibrils
Gene Ontology:
Molecular function: extracellular matrix structural constituent; heme binding; laminin-1 binding; oxidoreductase activity, acting on peroxide as acceptor; peroxidase activity; interleukin-1 receptor antagonist activity
Biological process: angiogenesis; basement membrane assembly; collagen fibril organization; extracellular matrix organization; hydrogen peroxide catabolic process; protein homooligomerization; protein homotrimerization; basement membrane organization; cell adhesion; immune response; cellular oxidant detoxification; eye development; negative regulation of cytokine-mediated signaling pathway; response to oxidative stress
Cellular component: cell surface; endoplasmic reticulum; extracellular exosome; extracellular matrix; extracellular region; basement membrane
Genetic constraint (gnomAD): Loss-of-function variants: 67 observed, 121.34 expected, observed/expected ratio (o/e) 0.55, 90% interval 0.45 to 0.68. The upper end of that interval is the gene's LOEUF score, 0.68, which puts it in group 2 of 6, group 1 being the genes least tolerant of losing a copy. Missense variants: 1,770 observed, 1,956.8 expected, observed/expected ratio (o/e) 0.9, 90% interval 0.87 to 0.94. Synonymous variants: 891 observed, 823.03 expected, observed/expected ratio (o/e) 1.08, 90% interval 1.02 to 1.14.
Gene-disease validity (ClinGen):
ClinGen rates the evidence that PXDN causes each of these diseases.
anterior segment dysgenesis 7 (autosomal recessive): Definitive. Any anterior segment dysgenesis in which the cause of the disease is a mutation in the PXDN gene.
Homologues: Orthologues: chimpanzee PXDN (99% identical), macaque PXDN (97% identical), guinea pig PXDN (91% identical), mouse Pxdn (91% identical), rat Pxdn (91% identical), dog PXDN (90% identical), pig PXDN (88% identical), rabbit PXDN (85% identical), tropical clawed frog pxdn (79% identical), zebrafish pxdn (74% identical), Drosophila melanogaster Pxn (43% identical), Caenorhabditis elegans pxn-2 (34% identical), and 6 more. Paralogues in human: PXDNL (60% identical), TPO (22% identical), MPO (21% identical), EPX (20% identical), LPO (18% identical).
Diseases named in the same sentence as PXDN in open-access papers:
PXDN is named in the same sentence as 119 diseases in open-access papers, as found by Europe PMC text mining. Sharing a sentence is not in itself a finding about the gene and the disease. The quoted sentences say what the papers report.
ovarian carcinoma (14 papers, 2010 to 2025). A malignant neoplasm originating from the surface ovarian epithelium. "Peroxidasin (PXDN) is a BM-associated protein with peroxidase activity that promotes the proliferation, invasion, and migration of ovarian cancer cells, and PXDN overexpression has been correlated with an unfavorable prognosis." (PMID 36353536, 2022). "High expression of the extracellular matrix protein PXDN has been linked to proliferation, invasion, and migration of ovarian cancer cell lines, potentially causing an association with poor prognosis in ovarian cancer." (PMID 33572894, 2021). "Furthermore, high PXDN expression in ovarian cancer has been linked to increased malignancy and poor patient outcome." (PMID 34964086, 2021). "In ovarian cancer, PXDN upregulation portends poor prognosis, and its knockout attenuates proliferation, invasion, and migration." (PMID 41413560, 2025). "Previous studies in glioblastoma and ovarian cancer have noted a correlation between PXDN and PI3K/AKT signaling." (PMID 41413560, 2025). "Recently, many studies have found that PXDN plays an important role in tumor tumorigenesis and development, such as in oral cancer and ovarian cancer." (PMID 39399179, 2024). "siRNA knockdown of PXDN in HEY ovarian cancer cells also reduced phosphorylation of PI3K/Akt, leading to reduced invasion and migration." (PMID 37801286, 2023). "In ovarian cancer patient tumours, high expression of PXDN is associated with smaller tumours, yet in vitro depletion of PXDN in HEY human ovarian cancer cells reduced proliferation and migration." (PMID 37801286, 2023). "There were significant differences in the PXDN protein expressions of seven tumors, including those of ovarian cancer, RCC, UCEC, pancreatic cancer, head and neck carcinoma, glioblastoma, and liver cancer." (PMID 35982948, 2022). "Previous studies reported that PXDN was significantly upregulated in oral squamous cell carcinoma and ovarian cancer." (PMID 36118855, 2022). "Overexpression of PXDN is found in ovarian cancer, melanoma, oral squamous cell carcinoma, and prostate cancer, associated with poor prognosis." (PMID 36245971, 2022). "Conversely, in vitro knock down of PXDN in HEY human ovarian carcinoma cell line decreased invasion, migration and proliferation, supporting the link between PXDN and malignant phenotype." (PMID 34964086, 2021). "PXDN is a peroxidase previously investigated in the context of ovarian cancer where the knockdown of this gene inhibits cellular proliferation, invasion and migration." (PMID 32042028, 2020). "PXDN may also contribute to tumor proliferation, invasion, and migration in ovarian cancer by regulating the PI3K/Akt pathway." (PMID 35982948, 2022). "In addition to melanoma, PXDN was also detected in tumors such as breast cancer, colon cancer, glioblastoma and ovarian cancer." (PMID 27172792, 2016). "Compared with matched healthy tissue, PXDN is up-regulated in a number of different cancers including melanoma, sarcoma, glioblastoma, oral carcinoma, prostate and testicular cancer, ovarian cancer, pancreatic cancer, thyroid cancer, head and neck cancer and stomach cancer." (PMID 37801286, 2023). "The results showed that the total protein expression of PXDN was significantly higher in PAAD, HCC, GBM, HNSC, Clear cell RCC, breast cancer, and ovarian cancer tissues than in normal tissues." (PMID 39399179, 2024). "PXDN also has an essential role in accelerting various cancer types, such as oral squamous cell carcinoma (OSCC), melanoma, prostate cancer (PCa) and ovarian cancer (OC)." (PMID 36118855, 2022). "Additionally, in other types of epithelial cancers such as oral cavity squamous cell carcinoma, breast cancer, ovarian cancer, and lung cancer, overexpression of PRDX4 correlates with the metastatic potential again implicating an alternative possible role for PXDN in regulating metastasis." (PMID 31234468, 2019).
melanoma (12 papers, 2010 to 2026). A malignant, usually aggressive tumor composed of atypical, neoplastic melanocytes. "Here, we demonstrate that elevated PXDN expression is associated with poor prognosis and reduced survival in melanoma patients." (PMID 41601454, 2026). "Our previous GSEA of melanoma cell lines revealed association of GLIS3 with breast cancer (the same gene set that showed upregulation of PXDN), supporting its role in multiple tumour types." (PMID 27172792, 2016). "However, mutations in the PXDN gene appear frequently in uterine cancers, stomach cancer, melanoma and colon cancer." (PMID 37801286, 2023). "Functional studies revealed that PXDN depletion impairs melanoma cell proliferation, disrupts the cell cycle, and reduces melanoma cell invasive capacities." (PMID 41601454, 2026). "Overall, our study highlights PXDN as a critical regulator of melanoma cell biology and a potential therapeutic target for NK-cell-based immunotherapy in melanoma and other solid cancers." (PMID 41601454, 2026). "In a range of melanoma cell lines of varying aggressiveness, PXDN expression was higher in more mesenchymal-like cells, which has also been observed in some breast cancer models." (PMID 37801286, 2023). "Corroborating literature data, our analysis demonstrated that PXDN is significantly augmented in VGP melanoma." (PMID 35326089, 2022). "Peroxidasin (PXDN) was initially named melanoma gene 50 (MG50), due to its expression in melanoma samples, which was characterized as a potent melanoma-associated antigen." (PMID 35326089, 2022). "Silencing PXDN in mesenchymal melanoma cells blocked cellular invasion and this observation is consistent with a previous study showing that loss of PXDN in BeWo choriocarcinoma cells blocked cellular invasion and adhesion." (PMID 27172792, 2016). "Since PXDN, NTN4 and GLIS3 are involved in motility and associated with mesenchymal gene signature in melanoma cell lines, we investigated the association of these candidate proteins with markers of EMT in clinical samples." (PMID 27172792, 2016). "In this study we investigated three genes consistently upregulated in mesenchymal-like melanoma cells including Peroxidasin (PXDN), Netrin 4(NTN4) and GLIS Family Zinc Finger 3 (GLIS3)." (PMID 27172792, 2016). "In TCGA melanoma dataset, mutual exclusivity data from melanoma patients revealed that both PXDN and GLIS3 are co-expressed (Odds ratio = 2.23, p = .010, Fisher's exact test)." (PMID 27172792, 2016). "High expression of PXDN was found in most mesenchymal-like melanoma cell lines compared with epithelial-like melanoma cell lines." (PMID 27172792, 2016). "Melanoma cells were transfected with siRNA targeting PXDN, NTN4 or GLIS3, cultured as a hanging drop for 24 hours and introduced into the trunk neural tube of a developing chick embryo." (PMID 27172792, 2016). "Although this study shows an association between PXDN, NTN4, GLIS3 and SNAI1 and melanoma invasion, their roles in melanoma are most likely multifaceted." (PMID 27172792, 2016). "Furthermore, we found that secreted PXDN modulates anti-melanoma immunity by enhancing melanoma resistance to natural killer (NK)-cell-mediated cytotoxicity." (PMID 41601454, 2026). "Similarly, melanoma cell lines with invasive phenotypes show elevated PXDN levels, while PXDN silencing suppresses invasion in vitro." (PMID 41413560, 2025). "PXDN gene silencing led to reduced melanoma invasion in vitro and inhibited migration in vivo." (PMID 35326089, 2022). "PXDN has also been shown to be increased in melanoma as well as brain, kidney, and breast cancers." (PMID 31234468, 2019). "Since PXDN is a surface protein accessible to extracellular pharmaceutical compounds, it may prove to be a novel target for abrogating tumor invasion in melanoma." (PMID 27172792, 2016).
melanoma (continued). "PXDN, also known as Melanoma-associated gene-50 (MG50), encodes a new melanoma antigen containing at least six naturally expressed melanoma HLA class 1-restricted epitopes that are recognized by human cytolytic T lymphocytes, further indicating its potential clinical applications." (PMID 27172792, 2016). "Although PXDN was expressed in melanoma samples its physiological role remains largely unexplored." (PMID 27172792, 2016). "Finally, on a protein basis, the first human peroxidasin was detected in human colon cancer cells, but later also in squamous lung carcinoma cells, where it was initially named melanoma gene 50 (MG50)." (PMID 22976969, 2012). "According to our analysis, 66% of the isoforms presented differential expression on melanoma progression: NOS2, SOD1, NOX4, PRX3, PXDN and GPX1 are increased during melanoma progression, while CAT, GPX3, TXNIP, and PRX2 are decreased." (PMID 35326089, 2022). "The significant correlation between PXDN and GLIS3 expression with EMT markers that was observed in our melanoma cell line studies is therefore also confirmed in a large clinical tumor dataset." (PMID 27172792, 2016). "We then analysed the protein expression patterns of PXDN, NTN4 and GLIS3 in melanoma tumors by immunohistochemical staining of tissue microarrays (TMA) comprising tumors from patients with stage III and IV metastatic melanoma." (PMID 27172792, 2016). "Whole mount and cross-sections of embryos shows that fewer PXDN and GLIS3 siRNA treated melanoma cells migrated out of the neural tube compared to control siRNA treated cells in LM-MEL-77 and -46 (not shown)." (PMID 27172792, 2016). "We identified Peroxidasin (PXDN), Netrin 4 (NTN4) and GLIS Family Zinc Finger 3 (GLIS3) genes consistently elevated in invasive mesenchymal-like melanoma cells." (PMID 27172792, 2016). "Given that PXDN, NTN4 and GLIS3 can regulate invasion of melanoma cells in vitro, we evaluated the in vivo relevance of our data in melanoma tumors." (PMID 27172792, 2016). "The preceding experiments indicated that PXDN, NTN4 and GLIS3 are highly expressed in metastatic melanoma and play a role in promoting melanoma cell invasion in vitro." (PMID 27172792, 2016). "Through a knockdown approach and in vivo motility model, we demonstrate 3 novel molecular players PXDN, NTN4 and GLIS3 as critical factors of melanoma invasion." (PMID 27172792, 2016). "TGF-β1 induced EMT in melanoma by modulating ECM molecules and it is likely that PXDN represents an ECM molecule in melanoma mediating an EMT in a TGF-β1-dependent manner." (PMID 27172792, 2016). "Besides, iNOS, SOD1, NOX4, PRX3, PXDN and GPX1 are generally increased during melanoma progression, while CAT, GPX3, TXNIP and PRX2 are decreased." (PMID 35326089, 2022). "Transfection with a control siRNA did not alter the invasive ability of mesenchymal-like melanoma cell lines, while PXDN silencing in these cell lines resulted in a significant reduction of invasion." (PMID 27172792, 2016). "To verify that the effects of HO-1 on cell adhesion and PXDN expression are truly related to HO-1, we generated a HO-1 gain-of-function cell model using 607B melanoma cells, which have no detectable endogenous HO-1 expression." (PMID 20667089, 2010). "Besides that, the PXDN expression was relatively high in a few studies including breast, melanoma, ovarian as well as brain tumor samples and it is absent from the normal tissues." (PMID 30733560, 2019). "Our study suggests that PXDN, NTN4 and GLIS3 play a functional role in promoting melanoma cellular invasion, and therapeutic approaches directed toward inhibiting the action of these proteins may reduce the incidence or progression of metastasis in melanoma patients." (PMID 27172792, 2016). "Furthermore, migration of PXDN, NTN4 or GLIS3 siRNA transfected melanoma cells was inhibited following transplantation into the embryonic chicken neural tube compared to control siRNA transfected melanoma cells." (PMID 27172792, 2016).
melanoma (continued). "Interestingly, we discovered a significant negative correlation between PXDN expression and the estimated infiltration value of T cells in almost all tumor types (except melanoma), among which head and neck tumors, esophageal cancer, and pancreatic cancer were the most obvious." (PMID 39399179, 2024).
breast carcinoma (9 papers, 2010 to 2026). "In human breast cancers, PXDN expression shows compartment-specific associations with patient outcome, with high stromal PXDN, predominantly cancer-associated fibroblast (CAF)-derived, correlating with poor prognosis." (PMID 42291185, 2026). "In breast cancer, PXDN overexpression is associated with advanced tumor grade, lymph node metastasis, and distant dissemination; patients with high PXDN expression exhibit reduced disease-free and overall survival." (PMID 41413560, 2025). "Increased levels of PXDN in oral squamous cell carcinoma have also been associated with increased lymph-node metastasis and infiltration at the primary site, and high expression of PXDN is associated with shorter metastasis-free survival in breast cancer." (PMID 37801286, 2023). "PXDN was demonstrated as one of the highly regulated genes in plasma protein changes associated with tumor progression study in human breast cancer cells." (PMID 30733560, 2019). "Whether increased expression of PXDN could contribute to basal characteristics within these breast cancer subtypes, thereby causing increased metastatic potential, therapy resistance or both, remains a topic for further studies." (PMID 34964086, 2021). "Peroxidasin (PXDN), an extracellular peroxidase with established roles in collagen IV crosslinking, has been associated with poor outcomes in several cancers, but its role in breast cancer remains unclear." (PMID 42291185, 2026). "On the other hand, breast cancer cells with siRNA knockdown of PXDN showed decreased proliferation whilst maintaining Akt and ERK phosphorylation." (PMID 37801286, 2023). "There is some evidence to suggest that PXDN expression is highest in mid-stage disease in breast cancer, and begins to decrease again at later stages of disease, although what this might mean biologically is unknown." (PMID 37801286, 2023). "Immunohistochemistry of three subtypes of breast cancer (ER-positive, HER2-positive and Triple negative) revealed that PXDN was expressed in cancer cells." (PMID 34964086, 2021). "Elevated PXDN was among the main ECM effectors identified in conditioned media from bone marrow derived mesenchymal stromal cells that induced migration of both PC3 prostate and MDA-MB-231 breast cancer cells." (PMID 37801286, 2023). "Results from the Gene expression-based Outcome for Breast Cancer Online (GOBO) database showed that women with basal and HER2-positive tumors that had high PXDN expression had poorer distant metastasis free survival (DMFS) compared to women with low PXDN-expressing tumors." (PMID 34964086, 2021).